KIRREL1 (kirre like nephrin family adhesion molecule 1)
Description:
Required for proper function of the glomerular filtration barrier. It is involved in the maintenance of a stable podocyte architecture with interdigitating foot processes connected by specialized cell-cell junctions, known as the slit diaphragm. It is a signaling protein that needs the presence of TEC kinases to fully trans-activate the transcription factor AP-1 (By similarity).
Synonyms: KIRREL; NEPH1; NPHS23
Tractability: Antibody: UniProt places it where antibodies can reach, with high confidence; its Gene Ontology location is reachable by antibodies, with high confidence; UniProt predicts a signal peptide or a membrane-spanning region. PROTAC: ubiquitination databases record sites on it.
Gene: Protein-coding gene on chromosome 1 (157,993,273 to 158,100,262, forward strand). Ensembl gene ENSG00000183853.
Subcellular location: Cell membrane
Pathways (Reactome):
Cell-Cell communication: Nephrin family interactions
Gene Ontology:
Molecular function: myosin binding; protein binding; cell adhesion molecule binding
Biological process: cell-cell junction maintenance; glomerular filtration; cell-cell adhesion
Cellular component: cell-cell junction; perinuclear region of cytoplasm; plasma membrane; cell projection membrane; dendritic shaft; membrane raft
Genetic constraint (gnomAD): Loss-of-function variants: 25 observed, 84.66 expected, observed/expected ratio (o/e) 0.3, 90% interval 0.21 to 0.41. The upper end of that interval is the gene's LOEUF score, 0.41, which puts it in group 1 of 6, group 1 being the genes least tolerant of losing a copy. Missense variants: 812 observed, 1,062.6 expected, observed/expected ratio (o/e) 0.76, 90% interval 0.72 to 0.81. Synonymous variants: 388 observed, 425.5 expected, observed/expected ratio (o/e) 0.91, 90% interval 0.84 to 0.99.
Homologues: Orthologues: chimpanzee KIRREL1 (99% identical), pig KIRREL1 (99% identical), guinea pig KIRREL1 (98% identical), macaque KIRREL1 (98% identical), mouse Kirrel1 (95% identical), rat Kirrel1 (95% identical), dog KIRREL1 (95% identical), rabbit KIRREL1 (87% identical), tropical clawed frog kirrel1 (79% identical), zebrafish kirrel1a (64% identical), zebrafish kirrel1b (60% identical), Drosophila melanogaster kirre (29% identical), and 5 more. Paralogues in human: KIRREL3 (45% identical), KIRREL2 (34% identical), NPHS1 (23% identical).
Diseases named in the same sentence as KIRREL1 in open-access papers:
KIRREL1 is named in the same sentence as 22 diseases in open-access papers, as found by Europe PMC text mining. Sharing a sentence is not in itself a finding about the gene and the disease. The quoted sentences say what the papers report.
tumour (5 papers, 2019 to 2024). "KIRREL1 is broadly expressed in different tissues and knockout of KIRREL1 increases proliferation of tumor cells of different lineages." (PMID 35177623, 2022).
cancer (4 papers, 2019 to 2024). A tumor composed of atypical neoplastic, often pleomorphic cells that invade other tissues. "Using these large publicly available datasets, we analyzed the effect of KIRREL1 knockout in more than 700 cancer cell lines (CRISPR Avana Public 20Q3)." (PMID 35177623, 2022). "Next, we plotted KIRREL1 mRNA expression over the KIRREL1 dependency score (CERES) for over 700 cancer cell lines." (PMID 35177623, 2022). "Additional studies are needed to further examine the function of KIRREL1 in different cancers." (PMID 35177623, 2022). "Remarkably, among the top genes, in addition to some important well-known genes for each of the cancer types, we also identified three genes APOBEC3H, KIRREL1, and FAM166B, that are significantly correlated with OS for CSCC and HGSOC patients, respectively." (PMID 38172536, 2024). "Analyzing pan-cancer CRISPR proliferation screen data reveals KIRREL1 as the top plasma membrane protein showing strong correlation with known Hippo regulators, highlighting a critical role of KIRREL1 in regulating Hippo signaling and cell proliferation." (PMID 35177623, 2022). "KIRREL1 knockout led to a significant increase in the expression of YAP target genes CTGF, CYR61, and ANKRD1, suggesting that KIRREL1 restricts YAP/TAZ activity in these cancer cell lines." (PMID 35177623, 2022).
KIRREL1 also shares sentences with these, for which no sentence is quoted: melanoma (4 papers); nephrotic syndrome (4); breast carcinoma (2); gastric cancer (2); benign fibrous histiocytoma (1); colon cancer (1); cutaneous melanoma (1); focal segmental glomerulosclerosis (1); glomerular disease (1); glomerulonephritis (1); glomerulosclerosis (1); hypercholesterolaemia (1); Hypertension (1); infection (1); lung squamous cell carcinoma (1); nephrosis (1); osteosarcoma (1); ovarian carcinoma (1); pancreatic cancer (1); pulmonary arterial hypertension (1).